CD4 (CD4 molecule)
Diseases named in the same sentence as CD4 in open-access papers (continued):
Sharing a sentence is not in itself a finding about the gene and the disease.
tumor (continued). "High-risk patients, however, had significantly higher proportions of tumor-infiltrating native B cells, plasma cells, CD8 T cells, CD4 memory-activated T cells, M1 macrophages and activated mast cells." (PMID 36674979, 2023). "In the A20 model, we and others have shown IT injections of CpG can increase OX40 expression on CD4 + effector and CD8 + T cells in the tumor microenvironment (TME)." (PMID 37016127, 2023). "The results were further correlated with the tumor growth, CD4+ and CD8+ T cell frequencies in primary tumor-drainage lymph node (TDLN) and spleen, and the changes in apoptosis- and immune-related proteins." (PMID 37242761, 2023). "Accurate monitoring of CD4+ and CD8+ T-cell responses to tumor antigens is critical for the development of effective vaccines." (PMID 36765532, 2023). "The immune cell status in tumor tissues was analyzed by measuring CD4+ T, CD8+ T, and NK cells of tumor‐infiltrating lymphocytes (TILs)." (PMID 37097643, 2023). "Higher on-treatment PD-1-positive-expressed CD4+ and CD8+ T cells within the 100-μm distance to tumor cells predicted longer OS." (PMID 37275884, 2023). "It plays a crucial inhibitory role in the tumor infiltration of CD4+ CD25+ regulatory T cells and its administration was demonstrated to delay tumor progression and survival in an EL-4 lymphoma model." (PMID 37372022, 2023). "CD8 + T cells are the only effector responsible for tumor clearance in the induction phase, while CD8 + and CD4 + T cells are involved in the memory phase." (PMID 37381018, 2023). "Results showed that the number of CD3+CD4+ T and CD3+CD8 + T cells in tumor from the DM‐CRC group was less than that in the CRC group." (PMID 36999930, 2023). "We next examined T cell infiltration in tumor tissues following anti-EN treatment and found that it increased for both CD8+ and CD4+ T cells compared to the control group." (PMID 36646951, 2023). "CD4+ and CD8+ T cells in the untreated tumor expressed a more clonal, extremely private TCR repertoire that was unshared with circulating T cells." (PMID 37209684, 2023). "Conversely, the infiltration of CD4+ and CD8+ T cells was significantly increased in TME, suggesting that the anti-tumor immune response was enhanced." (PMID 36675491, 2023). "The results revealed that CD4+ and CD8+ T cells in GC tissues with high (+++) C5aR1 levels were particularly clustered in the peripheral tumor stroma, with a small proportion of immune cells infiltrating the stroma of the parenchyma of tumor mass." (PMID 36508191, 2023). "Single-cell RNA sequencing (scRNA-seq) revealed that OV-mOX40L treatment activated tumor-infiltrating CD4 and CD8 T cells and decreased Tregs, along with the reprogramming of macrophages and neutrophils to a more pro-inflammatory anti-tumor state." (PMID 37554264, 2023). "An effective immune response relies on the priming of tumor-specific CD8 + T cells and CD4 + Th1 cells." (PMID 37723510, 2023). "On the other hand, the CD3+, CD4+, and CD8+ T cells were independently related to tumor recurrence, according to previous literature." (PMID 37050932, 2023). "Increasing evidence suggests that activation of immune cells (e.g., CD4, CD8, and NK cells) can kill tumour cells through mechanisms at the molecular level." (PMID 37990103, 2023). "Through the production of cytokines, these helper CD4+ T lymphocytes can function in maintaining and enhancing the activity of the cytotoxic CD8+ T lymphocytes; thus, they exhibit anti-tumor immune responses." (PMID 37345111, 2023). "TILs are lymphocytes isolated from tumor tissues and mainly include CD3+ T cells, CD4+ T cells, and CD8+ T cells, especially CD8+ T cells, which are the basis for producing an effect of immunotherapy." (PMID 37207207, 2023). "Analysis of cell populations in immunocompetent models, however, showed a decreased content in total T cells, CD4+ and CD8+ cells in tumor site, as well as monocyte-derived dendritic in both in tumor and in spleen." (PMID 37223101, 2023).
tumor (continued). "On the one hand, the expression level of SLC35A2 exhibited a weak positive correlation with the infiltration level of CD4+T cells, and the correlation suggested the role of SLC35A2 in the regulation of STAD tumor immunology." (PMID 37467193, 2023). "Treatment of anti-CTLA4 in combination with cisplatin and anti-PD-1 enhanced antitumor immunity in TNBC, involved with activation of tumor-infiltrating cytotoxic CD8 and CD4 T cells." (PMID 37838657, 2023). "As in the initiation of anti-viral T cell responses, Batf3 and IRF8 dependent cDC1 have been shown to be critical in the initiation of anti-tumour CD8+ T cell responses with cDC2 having a central role in driving the CD4+ T cell response." (PMID 37139854, 2023). "After epitope–MHC complexes are transported to the surface of tumor cells, antigen-presenting cells help induce CD8+ and CD4+ T cells." (PMID 37513844, 2023). "CTLA-4 receptors are expressed on activated CD4+ and CD8+ T cells and on Treg cells, as well as on tumour cells themselves." (PMID 37468749, 2023). "An “immune-inflamed” tumor is characterized by the infiltration of CD8+ and CD4+ T cells, B cells and NK cells, indicating a better response to ICI." (PMID 36826142, 2023). "We observed a poor infiltration of CD8+ and CD4+ T cells and an increased frequency of recurrence in pMMR/MSS CRC with the reduced expression or lost expression of cGAS-STING in tumor cells." (PMID 37345163, 2023). "Blocking TLR1/2 signaling significantly reduced the therapeutic efficacy of the immunogenic chemotherapeutic agent, resulting in reduced infiltration of DCs, CD4, and CD8 within the tumor microenvironment." (PMID 37945630, 2023). "The results exhibited increased expression of CD4+ T cells, CD8+ T cells, TAMs (F4/80+ CD11b+), and PD-1+ cells in the tumor tissue." (PMID 37189408, 2023). "We found that, in LUAD, CXCR4 was moderately negatively correlated with tumor purity, and moderately positively correlated with the tumor infiltration of B cells, CD8+ T cells, CD4+ T cells, macrophages, neutrophils, and DC cells." (PMID 36308553, 2023). "This induces the activation of CD4+ and CD8+ T-cells, which influences cytokine expression (TNF-α, IFN-γ, IL-2) and stimulates tumor cell killing." (PMID 38035338, 2023). "CD4+ helper T cells are important regulatory cells providing help to other immune cells, including CD8+ T cells, to mount an effective anti-tumor response." (PMID 37345086, 2023). "T-lymphocytes (CD3, CD4, CD8) and macrophages (CD68, CD163) were also present in tumour cell areas (iTILs) (B + D)." (PMID 36726072, 2023). "Next we found that both tumor and non-tumor tissues were infiltrated mainly by macrophages M2 and CD4 memory resting T cells, T cells follicular helper (Tfh) and Tregs expressed higher in tumor while CD8 expressed higher in non-tumor." (PMID 37313417, 2023). "To further investigate the mechanism of the anti-tumor immune response, we analyzed the percentage of CD8 + and CD4 + T cells in the tumor tissues of all groups." (PMID 37872620, 2023). "The CD4 T cells demonstrated expression of the immune checkpoint molecules TIM-3 and PDL-1, both with an immunosuppressive effect in the tumor and interface ROI." (PMID 36980192, 2023). "TCR can be used to identify naturally tumor-reactive T cells, but little is known about the differences in the TCR repertoires of CD4+ and CD8+ TILs." (PMID 37600765, 2023). "In a mouse MC38 tumor model, we demonstrated that IL21 is produced by hyperactivated/exhausted CD4+ T cells in the TME." (PMID 37546701, 2023). "The CD4 and CD8 TCR clonotype response in spleen and peritoneum to IP tumor challenge was compared in donor animals cured of implanted tumor by rrVSV oncolytic immunotherapy and host animals cured by T-cell transfer from the donor animals." (PMID 37033929, 2023). "The tumor regression induced by combination regimens requires CD4+ and CD8+ T cells and tumoricidal myeloid cells, indicative of an immune-based tumor regression mechanism." (PMID 38125944, 2023).
tumor (continued). "‘s study in rectal cancer found that mice treated with RT+IL-2 had a higher percentage of CD4+T cells but a lower percentage of Tregs and MDSC in splenocytes, Administering IL-2 significantly improved the anti-tumour impact of RT." (PMID 38259489, 2023). "Pre- and post-treatment tumor tissue analysis indicated comparable levels of T-cell infiltration, but there was evidence of CD8+ and CD4+ activation after treatment." (PMID 38077386, 2023). "In a bilateral CT26 model, the combination of NaLnF4@MOF (8.4 mg/mL) PDT with α-PD-L1 (50 μg/mice) injection raised the amount of tumor-infiltrating CD45+ T cells, CD4+ T cells, CD8+ T cells, and NK cells in primary and distant tumors." (PMID 36987269, 2023). "B7-H3 inhibition in mTORC1-hyperactive cells suppresses tumor growth by increasing IFN-γ responses and major histocompatibility complex II (MHC-II) expression in the tumor cells and enhancing CD38+CD39+CD4+ T lymphocyte-mediated antitumor immunity." (PMID 36869048, 2023). "Taking the tumor region and IM together, high CD3+ (DFS, P=0.0014; OS, P=0.0031) and CD4+ (DFS, P=0.0101; OS, P=0.0106) signals were significantly correlated with better survival." (PMID 37090736, 2023). "Due to the fact that CD4+ CTL attracted attention in solid cancers only recently, there is still limited but growing data about their cytotoxic activity against tumor cells." (PMID 37965314, 2023). "According to the current theory, the recognition and clearance of tumor cells require the involvement of inflammatory cells from the innate and acquired immune systems, primarily CD8‐positive (+) T lymphocytes, CD4+ T lymphocytes, and macrophages." (PMID 37698123, 2023). "Immune effector cells, like CD4+ and CD8+ T lymphocytes, play a direct or indirect role in the elimination of tumor cells through the induction of channel apoptosis and/or the production of cytokines in both the innate and adaptive immune responses." (PMID 37795038, 2023). "A flow cytometric analysis of CD3+, CD4+, and CD8+ T cell populations within the intratumoral cells revealed that the proportion of tumor infiltrating T cells, especially CD8+ T cells, was significantly higher in the KO mice than in WT." (PMID 37664721, 2023). "The treatment also resulted in a significant increase in the numbers of CD4+ and CD8+ in the blood and tumor tissue samples." (PMID 37373523, 2023). "This siRNA delivery system has been found to enter both CD4+ and CD8+ T cell subsets at tumour sites in vitro and in vivo." (PMID 36980527, 2023). "Bone metastasis of PCa is related to tumor stage, N stage, Gleason score, ISUP, PSA, survival status, CD4+ TILs density, and NSD2 expression (P < 0.05)." (PMID 38062230, 2023). "It has been shown that antibodies targeting VEGFR2 can switch the immunophenotype of TAMs, thereby promoting CD4+ and CD8+ T-cell function and tumor infiltration." (PMID 38264642, 2023). "In the spatial analysis, helper CD4+Ts and CD8+Ts, M1 macrophages and pDCs were proximal to tumour cells; other immune cell types were more evenly distributed, while mature DCs were predominantly distant from tumour cells." (PMID 37835491, 2023). "Specifically, immunostaining showed increased numbers of CD4+ cells and a highly significant increase in CD8+ T cells within the tumour milieux of patients who received vitamin D3 treatment." (PMID 37299554, 2023). "Nevertheless, a role for CD4 CTL in anti-tumor immunity is increasingly being appreciated, especially in HLA class II+ tumor types in patients." (PMID 37185301, 2023). "The expression of TNFR2 by tumor-infiltrating CD8 T cells appeared to be less homogeneous and relatively discrete, as compared with its expression in CD4 T cells." (PMID 36865537, 2023). "The tumor microenvironment contains tumor-infiltrated cells, such as CD4+, CD8+ T-cells, and regulatory T-cells (Treg), which are crucial for establishing the host immune system against the tumor." (PMID 37764996, 2023).
tumor (continued). "In the tumor microenvironment, HCC patients with low PRDX1 expression had more significant infiltration levels of M0 macrophages, M1 macrophages, CD4+ Th1 cells, CD4+ Th2 cells, myeloid dendritic cells, monocytes, and lymphoid progenitor cells." (PMID 37842089, 2023). "The PD-1-negative-expressed CD4+ and CD8+ T cells were located significantly nearer to the tumor cells than PD-1-positive-expressed T cells." (PMID 37275884, 2023). "CD4+ helper T cells provide help signals to other immune cells, while CD8+ CTLs recognize and eliminate tumor cells expressing the presented antigens." (PMID 37681891, 2023). "The adjusted results based on tumor purity showed a significant correlation between HLA-DPA1, CD4, and all immune cell types (all P < 0.05)." (PMID 36627705, 2023). "While most tumor immunotherapies aimed at harnessing the killing activity of CD8+ T cells, there is increasing evidence that CD4+ T cells also play a major role during antitumor immune response both in preclinical models and in patients with cancer." (PMID 37248395, 2023). "Patients with high PD-L1 expression and high CD3+, CD4+, or CD8+ T cell expression in tumor tissues showed better prognosis than other subgroups, and the differences were statistically significant." (PMID 38050283, 2023). "This has suggested impaired effector function by tumor-infiltrating CD8+ T cells and increased immunosuppression by CD4+ Tregs cells." (PMID 37190304, 2023). "The infiltration of CD4 and CD8 T cells, as well as the levels of the TEX marker genes (HAVCR2, TIGIT, CTLA4, LAG3, and PD1) and tumor stem cell marker genes (CD44 and PROM1), were all greater in tissue samples with high TEXSRGs-score." (PMID 37957420, 2023). "The immune-inflamed phenotype was defined by the presence of T cells that express CD4 and CD8 in the tumor parenchyma, in conjunction with myeloid cells and monocytes." (PMID 37547754, 2023). "The release of tumor antigens and APC activation after IR are key events in the activation of CD8+ and CD4+ T cells." (PMID 37108522, 2023). "In triple negative and HER2+ breast cancer cells, treatment with either CD4+ Th1 cells or Th1 cytokines TNF-α and IFN-γ induced apoptosis and tumor senescence." (PMID 36769195, 2023). "The combination therapy significantly increased the infiltration of CD4+ T cells, CD8+ T cells, as well as the population of IFN-γ+ CD4+ T cells and IFN-γ+ CD8+ T cells in the tumor immune microenvironment compared to those in the other groups." (PMID 37291128, 2023). "Numerous studies have used nanoparticles as delivery systems for antigens and costimulatory molecules to be co-ordinately delivered to APCs, resulting in improved CD4+ and CD8+ T responses against tumour." (PMID 36851335, 2023). "TACE has also been shown to increase the CD4+/CD8+ T cell ratio and the frequency of tumor-specific CD4+ T cells." (PMID 37511193, 2023). "We emphasized that these cells are indispensable for the increase of IFNɣ-producing CD4+ and CD8+ TILs and subsequent tumor growth control." (PMID 36875124, 2023). "IL-12 induces IFN-γ release and infiltration of CD4+, CD8+ T cells, NK cells, and dendritic cells into the tumor, evidencing its potential use in immunotherapy." (PMID 36831131, 2023). "A high PANoptosis signature score correlated with infiltration of immune cells, such as CD4, CD8, and natural killer cells, in the TME, which promote tumor immunity." (PMID 37547288, 2023). "Lower-grade tumours featured greater interaction between tumour cells and both CD8+ and CD4+Ts; meanwhile, though M2-like macrophages and CD8+Ts coexist across tumour grades, their degree of interaction increases as tumour grade increases." (PMID 37835491, 2023). "We observed that, in biologically old patients, a lower infiltration of CD163+ macrophages as well as CD4+ and CD8+ lymphocytes was found in the tumor microenvironment." (PMID 37568649, 2023).
tumor (continued). "And it has been demonstrated that PD-1 expression increased in CCA patients with CD4+ and CD8+ tumor‐infiltrating lymphocytes (TILs), and the level of effector cytokines in TILs was positively correlated with nivolumab." (PMID 37064120, 2023). "In this network meta-analysis, the clinical effective rate, KPS score, T cell subsets (CD3+, CD4+, CD4+/CD8+), serum tumor markers (CA125, HE4), and adverse events were all shown to be 5 interesting outcomes." (PMID 37832073, 2023). "Tumor growth slows from the second phase, which includes B cells (CD20+) and two subsets of T cells, T helper cells (CD4+), and cytotoxic T cells (CD8+)." (PMID 38001643, 2023). "Compared to GBM, we observed a significant increase in the presence of tumor-infiltrating CD3+ T cells in BrM both in the CD8+ and in the CD4+ subsets." (PMID 37936683, 2023). "The number of CD4+ and CD8+ T cells in the tumor decreased at the same time as PD-1 expression and TCR diversity declined." (PMID 37006319, 2023). "The contribution of CD4+ and CD8+ T cells to l-fuc-triggered tumor suppression was assessed by immunodepletion in the SW1 model." (PMID 36690875, 2023). "GBM’s tumor-infiltrating lymphocytes (TILs) are low, while the content of CD4 + T cells and CD8 + T cells increases with tumor malignancy." (PMID 37853449, 2023). "EVs derived from CD4 T cells, specifically carrying miR-25-3p, miR-155-5p, miR-215-5p, and miR-375, have been identified as key instigators of CD8 T cell-mediated anti-tumor responses." (PMID 38087360, 2023). "We established that HELC therapy induces an immune response from tumors with DC, CD4 and CD8 positive tumor tissue after treatment." (PMID 37336938, 2023). "In this study, we found that propolis administration increased the density of CD3+ and CD4+ TILs and decreased the density of FOXP3 lymphocytes in the lamina propria of the tumor microenvironment in the mice with early stage CRC." (PMID 37960147, 2023). "Consistent with previous reports, we find a strong correlation between the induction of CD8+ and CD4+ reactive T cells by APC-targeted DNA vaccines and anti-tumor efficacy, indicating that neoepitope-induced T-cells mediate the anti-tumor effect." (PMID 37720215, 2023). "Top2A vaccination increased CD4+ and CD8+ tumor infiltrating lymphocytes as well as the percentage of the functionally activated CD4+ and CD8+ cells in the spleens from the vaccinated mice." (PMID 37880313, 2023). "Mechanism study revealed that EFL1 intervention enhanced the ratios of CD4+ and CD8+ and CD49b+(NK) T lymphocytes and decreased Treg cells through downregulating DDR1 in the tumor of SHI mice." (PMID 37709489, 2023). "It has been proven in mouse cancer models that simultaneous blocking of LAG-3 and PD-1 co-expressed on CD4+ and CD8+ TILs can synergistically improve anti-tumor CD8+ T cell responses." (PMID 37841254, 2023). "The patients having higher tumor CD4+ T cells at baseline had worse OS and worse PFS compared with those having lower baseline tumor CD4+ T cells." (PMID 37275884, 2023). "The combination of CCKR blockade results in a significant decrease in tumor FOXP3+ Tregs and an increase in CD4+ and CD8+ lymphocytes." (PMID 37529035, 2023). "In our study, TICAM1 was highly expressed in the CHOL group and was positively correlated with resting central memory CD4+ T cells and NK cell activation, suggesting that the TICAM1 gene product is involved in the tumor microenvironment." (PMID 36936916, 2023). "Microglia/macrophage motility and activation (Iba1, CD68), programmed death-ligand 1 and CD4+ T cells were reduced, and homeostatic microglia (P2RY12) were increased in the invasive margins compared with the tumour core." (PMID 37324244, 2023). "In contrast, none of S100A5 expression tumors exhibited an inflamed phenotype, with numerous CD4+ and CD8+ T cells infiltrating the tumor regions (inflamed)." (PMID 37414584, 2023).